HOTAIR (HOX transcript antisense RNA)
Diseases named in the same sentence as HOTAIR in open-access papers (continued):
Sharing a sentence is not in itself a finding about the gene and the disease.
breast cancer (continued). "In particular, HOTAIR is strongly upregulated in primary breast tumors and breast cancer metastases and overexpression studies performed in a cell line model of breast cancer have shown that elevated HOTAIR levels resulted in the relocalization of PRC2 to several hundred genes." (PMID 29443889, 2018). "Our study revealed a novel epigenetic mechanism underlying CAF-induced tumor growth and metastasis, the TGF-ß1/HOTAIR axis controls the development and progression of breast cancer, which supports the pursuit of these molecules as targets of breast cancer treatment." (PMID 29325547, 2018). "Interestingly, HOTAIR is also regulated by estrogen and acts through estrogen receptors in ER+ breast cancer patients eluding to a feedback loop between the lncRNA and hormonal levels in normal individuals." (PMID 29732012, 2018). "In breast cancer metastasis HOTAIR is overexpressed more than 100-fold." (PMID 30687231, 2018). "Thus, we conclude that HOTAIR up-regulates Bcl-w to enhance cell proliferation through sequestering miR-206 in breast cancer." (PMID 29222472, 2017). "To uncover whether miR-206/Bcl-w signal participates in HOTAIR-mediated breast cancer cell proliferation, we performed MTT and BrdU incorporation assays in MCF-7 or T47D cells." (PMID 29222472, 2017). "Elevated overexpression of the lncRNA HOTAIR mediates invasion and metastasis in breast cancer." (PMID 28846832, 2017). "Interestingly, we find that HOTAIR increases Bcl-w expression via sequestering miR-206 at post-transcription level, leading to the promotion of breast cancer growth." (PMID 29222472, 2017). "Therefore, HOTAIR can be important for the aggressiveness of breast cancer, so it can be considered as a target in the therapy of highly invasive cases of this disease." (PMID 29469819, 2017). "Therefore, there are several mechanisms of the interplay between HOTAIR and autophagy important for breast cancer, but further studies are needed to determine more details of this interplay." (PMID 29469819, 2017). "To determine whether HOTAIR‐N accounts for increased expression of HOTAIR in breast cancer patient biopsies, we surveyed the TCGA Invasive Breast Carcinoma RNA‐Seq data." (PMID 28846832, 2017). "Moreover, the knockdown of HOTAIR by siRNA is correlated with a decreased colony forming capacity of colon and breast cancer cells." (PMID 29299179, 2017). "In addition, lncRNA HOTAIR, which is highly expressed in metastatic breast cancers, accelerates the EMT-dependent metastasis of breast cancer by inhibiting miR-7 through HoxD10 inhibition." (PMID 27992370, 2017). "This study was aimed to highlight the potential role of HOTAIR in breast cancer." (PMID 29209357, 2017). "Given that Bcl-w is an important pro-survival protein, we speculated that Bcl-w might be involved in HOTAIR-mediated breast cancer progression." (PMID 29222472, 2017). "Also, the same phytochemical compound was showed to be a down regulator of HOTAIR in breast cancer, an upregulated predictor of low survival rate, with the same anti-tumour activities as in the case of prostate cancer." (PMID 28587155, 2017). "Therefore, HOTAIR can be important for breast cancer progression, as it was shown that HOTAIR expression increased in primary breast cancer and metastases and the level of HOTAIR expression in primary tumors was a powerful indicator of metastasis." (PMID 29469819, 2017). "For example, disruption of the interaction between HOTAIR with PRC2 may decrease metastasis in breast cancer." (PMID 28829354, 2017). "Thus, we conclude that HOTAIR up-regulates Bcl-w through sequestering miR-206 at post-transcriptional level to enhance the breast cancer progression." (PMID 29222472, 2017). "Furthermore, qRT-PCR analysis demonstrated that HOTAIR expression was positively correlated with Bcl-w expression in clinical breast cancer tissues (Pearson’s correlation, R = 0.8451, p < 0.001)." (PMID 29222472, 2017).
breast cancer (continued). "Our finding provides new insights into the mechanism of breast cancer mediated by HOTAIR." (PMID 29222472, 2017). "However, because of the follow up limitations of TCGA cohort, further studies are necessary to reveal the role of HOTAIR in breast cancer initiation/progression in different cohorts with well annotation for tumor histology, and survival data." (PMID 29209357, 2017). "We gain novel insights into the understanding of breast cancer progression induced by HOTAIR." (PMID 29222472, 2017). "HOTAIR, the first discovered trans-acting lncRNA, has been found to be aberrantly overexpressed in many kinds of tumor tissues and cell lines such as gastric cancer, breast cancer, hepatic carcinoma, ovarian cancer and acute myeloid leukemia." (PMID 28207735, 2017). "Moreover, functional studies revealed that a high level of HOTAIR promoted the growth of breast cancer, whereas silencing of HOTAIR abolished tamoxifen-resistant cell growth." (PMID 27713133, 2017). "Similarly, increased expression of HOTAIR contributes to the breast cancer poor prognosis and metastasis." (PMID 28159929, 2017). "Therefore, the HBXIP/HOTAIR/LSD1 complex can be critical for transactivation by c-Myc in breast cancer and possibly for general oncogenic function of this oncogene." (PMID 29469819, 2017). "Clinically, overexpression of HOTAIR is a powerful predictor of overall survival and progression for several cancers including gastrointestinal stromal tumors, breast cancer, squamous cell carcinoma, nasopharyngeal carcinoma laryngeal, colon cancer, hepatocellular carcinoma and pancreatic cancer." (PMID 28376832, 2017). "Expression of HOTAIR isoforms in human breast cancer specimens." (PMID 28846832, 2017). "HOTAIR, the first lncRNA implicated in breast cancer, interacts with the PRC2 complex and LSD1 and drives transcriptional repression; overexpression of HOTAIR causes a global repression of tumor suppressors, which promotes breast cancer metastasis." (PMID 28558830, 2017). "On the contrary, Gupta considered that HOTAIR could reprogram chromatin state to promote breast cancer metastasis and death." (PMID 29113381, 2017). "Finally, the knockdown of TINCR, DSCAM-AS1 or HOTAIR inhibited breast cancer cell proliferation, increased apoptosis and inhibited cell cycle progression in vitro." (PMID 28738804, 2017). "The regulation of HOTAIR on Bcl-w in breast cancer development is unexplored." (PMID 29222472, 2017). "Thus, future studies are needed to explore the links between lncRNAs and estrogen receptors in breast cancers, as it is the case for H19 and HOTAIR." (PMID 27340923, 2016). "Inversely, HOTAIR depletion inhibits breast cancer cell invasiveness." (PMID 26992233, 2016). "As is well-known, HOTAIR could regulate breast cancer proliferation and chemo-resistance as an oncogenic lncRNA." (PMID 26910840, 2016). "Dp treatment down-regulates HOTAIR expression in breast carcinogenesis and breast cancer cells." (PMID 27388461, 2016). "HOTAIR is up-regulated in lung cancer, breast cancer, esophageal cancer, and GC." (PMID 27835600, 2016). "Interestingly, BRCA1, an important suppressor of breast cancer inhibits HOTAIR dependent PRC2 activity by competitive binding to its catalytic subunit EZH2." (PMID 25954300, 2015). "Moreover, we measured the expression of HOTAIR in breast cancer tissues (n = 20) and normal breast tissues (n = 20)." (PMID 25928008, 2015). "To study whether HOTAIR is regulated by E2 via GPER in breast cancer cells, we measured the mRNA levels of HOTAIR in breast cancer cells after treatment with E2." (PMID 25928008, 2015). "Since HOTAIR increases in both ER-positive and TN breast cancer, we supposed that estrogen may regulate HOTAIR expression through GPER." (PMID 25928008, 2015).
breast cancer (continued). "For example, lncRNAs such as HOTAIR (breast cancer), NKILA (breast cancer metastasis), NBAT1 (neuroblastoma), MALAT1 (lung, breast, prostate and cervix cancer), MDC1-AS (bladder cancer), lncRNA-886 (esophageal and gastric cancers) and PCAT-1 (prostate cancer) have been implicated in tumorigenesis." (PMID 26087192, 2015). "miR-148a level was negatively correlated with HOTAIR level in breast cancer patients." (PMID 25928008, 2015). "Furthermore, in a recent study, HOTAIR-mediated chromatin changes promoted breast cancer metastasis." (PMID 25405331, 2015). "Given the purported importance of HOTAIR in breast cancer, we sought to address the question of whether the expression of HOTAIR could be used as a surrogate for assessing nodal metastases." (PMID 25739705, 2015). "However, induction of gene expression was observed as a consequence of ectopic HOTAIR overexpression in MDA-MB-231 breast cancer cells and in our study at least as many genes became induced as down-regulated in the UC cell lines." (PMID 25994132, 2015). "In addition, estradiol induces HOTAIR expression through the suppression of miR-148a in breast cancer." (PMID 26183397, 2015). "HOTAIR has been demonstrated to be an oncogene to modulate the metastasis of breast cancer and NPC." (PMID 26448942, 2015). "Indeed, several dysregulated lncRNAs, such as HOTAIR and MALAT-1, have been found to be associated with breast cancer survival." (PMID 26549855, 2015). "HOTAIR, one of the important lncRNAs in the promotion of breast cancer migration, increases in both ER-positive and TN breast cancer, indicating that estrogen may regulate HOTAIR in a different way other than through ER." (PMID 25928008, 2015). "In addition, lncRNAs, such as HOTAIR, are involved in the development and progression of tumors, such as breast cancer." (PMID 25522749, 2015). "An in vitro functional study showed that HOTAIR overexpression in four different breast cancer cell lines could promote colony growth and invasion." (PMID 25739705, 2015). "A potential explanation for HOTAIR overexpression in breast cancer could be related to the presence of estrogen response elements in the HOTAIR promoter, leading to estradiol-induced HOTAIR expression." (PMID 25849966, 2015). "To investigate whether the expression of HOTAIR is changed in breast cancer patients, we collected PBMCs from 20 breast cancer patients and 20 normal women, and measured the HOTAIR levels using real-time PCR." (PMID 25928008, 2015). "Furthermore, we found that the miR-148a level in the PBMCs from the breast cancer patients was also negatively correlated with the HOTAIR level (R2 = 0.6492, P < 0.001)." (PMID 25928008, 2015). "HOTAIR has been known to induce tumor growth and metastasis in breast cancer." (PMID 25883211, 2015). "Furthermore, HOTAIR has promoted the migration and invasion of breast carcinoma cells, CRC cells, pancreatic cancer cells, NSCLC cells and ESCC cells." (PMID 25928008, 2015). "Overexpression of HOTAIR has been found in breast cancer, colorectal cancer, and hepatoma." (PMID 25334066, 2014). "Furthermore, HOTAIR promoted migration and invasion of breast carcinoma cells, CRC cells, pancreatic cancer cells, NSCLC cells, and ESCC cells." (PMID 24663081, 2014). "High expression of HOTAIR in breast cancer is a predictor of metastasis and poor outcome." (PMID 23936419, 2013). "HOTAIR is highly induced (up to 2,000-fold) in breast cancer metastatic tissues." (PMID 23862139, 2013). "HOTAIR was shown to be associated with metastasis in breast cancer patients, is a negative prognostic factor and exhibits pro-oncogenic activity in pancreatic cancer and predicts tumour recurrence in hepatocellular carcinoma." (PMID 23875687, 2013). "Ectopically expressed HOTAIR could confer the breast epithelial cancer cells with invasive and metastatic potential while its depletion in breast cancer cells abrogated these activities." (PMID 24013378, 2013).
breast cancer (continued). "In this study, using in situ hybridization to evaluate HOTAIR lncRNA expression and immunohistochemistry to evaluate protein expression of EZH2, we confirm that EZH2 and HOTAIR are coexpressed in breast cancer, as they have the same expression score 75.7% of the time (p<0.0001)." (PMID 23133536, 2012). "Also, HOTAIR Although HMGA2 is highly expressed in most malignant tumors, including ovarian and pancreatic cancer, there are limited studies on its association with tumor formation and progression in breast cancer." (PMID 40686703, 2025). "However, HOTAIR is regulated by estrogen via ER-α in ER-α-positive breast cancer." (PMID 41294885, 2025). "Notably, HOTAIR could serve as a molecular sponge for miR-20a-5p, promoting breast cancer progression and tumorigenesis by activating the expression of the HMGA2 protein." (PMID 38561760, 2024). "However, other studies reported a decrease in the expression of TUG1 by metformin in vascular wall cells, a decrease in the expression of HOTAIR by metformin in MDA-MB-231 breast cancer cells, and a decrease in the expression of MALAT1 by metformin in cervical cancer cells." (PMID 38053839, 2023). "Moreover, they found that HOTAIR expression in breast cancer cells can be induced by estradiol." (PMID 37308974, 2023). "In addition, HOTAIR could increase radioresistance in breast cancer by promoting HSPA1A expression through binding to miR-449b-5p in MDA-MB-231 cells." (PMID 36233075, 2022). "In this study, we generate a transgenic murine model with inducible human HOTAIR expression to mechanistically investigate how HOTAIR acts to promote breast cancer progression, and whether depletion of HOTAIR can serve as a therapeutic strategy for treating breast cancer in patients." (PMID 36579891, 2022). "Therefore, HOTAIR could be viewed as a potential therapeutic target in breast cancer; and its level in primary tumors is a powerful predictor of metastases and death." (PMID 36558071, 2022). "Notably, HOTAIR has been reported to function extensively as a ceRNA in breast cancer." (PMID 36233075, 2022). "Furthermore, the downregulation of HOTAIR may sensitize tumor cells to trastuzumab in breast cancer." (PMID 34405017, 2021). "Thus, HOTAIR has been postulated as putative breast cancer oncogene." (PMID 34869037, 2021). "Moreover, in recent years, the overexpression of HOTAIR can promote the occurrence and metastasis of breast cancer, colorectal cancer and ovarian cancer, whereas the proliferation and invasion ability of cancer cells can be effectively inhibited in the case of HOTAIR knockout." (PMID 33346222, 2020). "In addition, the conditioned medium of CAFs-derived from breast cancer could significantly enhance the expression of HOTAIR and promote the metastasis of breast cancer cells." (PMID 33520725, 2020). "And we found that miR-218 was up-regulated in HOTAIR knockdown cells, and the up-regulation of miR-218 promoted cells apoptosis and DNA damage after irradiation, suggesting miR-218 as a potential target of HOTAIR in the regulation of radiosensitivity of breast cancer." (PMID 30429228, 2019). "Similar results for HOTAIR’s potential to promote resistance to cisplatin or other types of chemotherapy drugs have been obtained for other types of cancer as well, such as hepatocellular carcinoma, breast cancer, gastric cancer, colorectal cancer, cervical cancer, and ovarian cancer." (PMID 30654440, 2019). "Moreover, in vitro studies have identified that the HOTAIR was robustly expressed in the basal-like breast cancer cells and the inhibition of HOTAIR could reduce the basal-like gene expression and growth." (PMID 29423075, 2018). "Therapeutically, HOTAIR and Bcl-w may serve as targets for breast cancer." (PMID 29222472, 2017). "Here, we are wondered whether HOTAIR is part of Bcl-w regulation process in breast cancer." (PMID 29222472, 2017).
breast cancer (continued). "A meta-analysis suggests that HOTAIR is important for lymph-node metastasis, which is an early, clinically detected step of tumor cell dissemination in most cancers, of special importance in breast cancer, as in this disease, manual control of axillary lymph nodes is a routine." (PMID 29469819, 2017). "Furthermore, Dp significantly down-regulated HOTAIR expression in breast cancer cells." (PMID 27388461, 2016). "In addition to breast cancer, overexpression of HOTAIR has been reported to be a marker for poor prognosis in various cancer types, including gastro-intestinal cancers, urologic cancers, gynecologic cancers, lung cancers and undifferentiated carcinoma of nasopharyngeal type." (PMID 27340923, 2016). "Finally, the lncRNA HOTAIR is highly expressed in metastatic breast cancer, and inhibition of HOTAIR expression may therefore prevent metastasis." (PMID 27229531, 2016). "HOTAIR expression is augmented in primary breast tumors and metastases, and HOTAIR expression level in primary tumors is a powerful predictor of metastases and death.Therefore, HOTAIR may be a potential therapy target in breast cancer." (PMID 25928008, 2015). "Here, we found that E2 could up-regulate HOTAIR levels through GPER in TN breast cancer cells." (PMID 25928008, 2015). "However, in TN breast cancer, HOTAIR is also up-regulated, indicating that HOTAIR may be regulated in a different way." (PMID 25928008, 2015). "A large number of studies have focused on its biological role and association with clinical prognosis, yet the precise factors regulating its expression remains largely unknown expect that HOTAIR is transcriptionally regulated by estradiol in breast cancer, which is quite tumor specific." (PMID 24953832, 2014). "In addition, aberrant expression of many other lncRNAs has also been reported to be involved in multiple tumors progression and can be used as prognostic indicators, for example enhanced HOTAIR expression can promote cells metastasis and serve as a prognostic factor of breast cancer." (PMID 24810364, 2014). "EZH2 knockdown followed by chromatin immunoprecipitation demonstrated that HOTAIR-mediated gene repression could be either PRC2-depedent or -independent in pancreatic cancer cells, although the PRC2 is necessary for HOTAIR target gene repression in breast cancer cell." (PMID 24013378, 2013). "Clinically, overexpression of HOTAIR is a powerful predictor of overall survival and progression for several cancers including pancreatic cancer, hepatocellular carcinoma, colon cancer, nasopharyngeal carcinoma laryngeal, squamous cell carcinoma, breast cancer and gastrointestinal stromal tumors." (PMID 23717443, 2013). "Thus, in breast carcinoma, there is increased HOTAIR expression and increased EZH2 expression." (PMID 23133536, 2012). "MALAT1, UCA1, CYTOR, HOTAIR, and GAS5 expressions were compared between breast cancer patients treated with tamoxifen alone (control) and those treated with tamoxifen plus NanoCurcumin (target group)." (PMID 41031251, 2025). "HOTAIR over expression in invasive ductal carcinoma leads to increased expression of DNA repair factors like KU70, KU80, DNA-PK and ATM regulating breast cancer cell proliferation by regulating apoptosis and the cell cycle." (PMID 39940704, 2025). "The interaction between HOTAIR and PRC2 has significant therapeutic implications for breast cancer metastasis." (PMID 39997609, 2025). "The expression levels of long non-coding RNAs (lncRNAs) HOTAIR, MALAT1, and UCA1, as well as cancer stem cell-related genes FOX, SNAIL, and ZEB, were analyzed in metastatic breast cancer stem cells (MBCSCs) compared to a healthy control group." (PMID 40781106, 2025). "First, expressions of HOTAIR/miR20a-5p/HMGA2 genes were quantified and compared in breast cancer patients (n = 40) and healthy controls (n = 10)." (PMID 40686703, 2025).